EGFR (epidermal growth factor receptor)
Diseases named in the same sentence as EGFR in open-access papers (continued):
Sharing a sentence is not in itself a finding about the gene and the disease.
bladder cancer (continued). "Our previous data indicated that the EGFR-AKT pathway mediated the aggressive tumor behavior in DNMT1-positive bladder cancer." (PMID 26090723, 2015). "It has been shown that AR can increase expression and activity of EGFR and a protein encoded by the ERBB2 (also known as Her2) gene, implying androgen-mediated bladder cancer tumorigenesis and clinical progression via the regulation of the EGFR/ERBB2 pathways." (PMID 26347776, 2015). "Accordingly, we suggested that the downregulation of miR-424 mediates the activation of EGFR signaling in DNMT1-positive bladder cancer." (PMID 26090723, 2015). "Overexpression of EGFR in bladder cancer has been widely reported and several studies have shown EGFR positivity to be associated with high tumor stage, tumor progression, and poor clinical outcome." (PMID 25866762, 2015). "The growth factor receptors including ERBB2, ERBB3 and EGFR have been found to be altered or amplified in bladder cancer and have the potential to activate PI3K/AKT signaling pathway." (PMID 26597249, 2015). "By profiling gene and protein expression of the human T24 bladder cancer cell compared with its metastatic derivative T24T, we found a striking inverse relationship between p27Kip1 and EGFR (epidermal growth factor receptor) expression." (PMID 25121353, 2014). "The epidermal growth factor receptor (EGFR) is also overexpressed by many carcinomas, including bladder cancers." (PMID 24964787, 2014). "It is well known that the EGF/EGFR pathway plays a critical role in bladder cancer development, progression and recurrence." (PMID 24801713, 2014). "An inverse relationship between p27Kip1 and EGFR expression in parental T24 human bladder cancer cells and various human cancer tissues was found." (PMID 25121353, 2014). "The present study has demonstrated that p27Kip1 suppresses JNK/c-Jun activation and EGFR expression in mouse MEFs and human bladder cancer cells, and the results obtained are consistent with those from human cancer specimens." (PMID 25121353, 2014). "In a study conducted by Liana Adam, miR-200 expression regulated the epithelial-to-mesenchymal transition in bladder cancer cells and reversed EGFR therapy resistance." (PMID 24650032, 2014). "The results of the present study demonstrate that p27Kip1 suppresses JNK/c-Jun activation and EGFR expression in MEFs and human bladder cancer cells, and the results obtained are consistent with those from human cancer specimens." (PMID 25121353, 2014). "Crosstalk of Met with the Src/EGFR signaling pathway has also been demonstrated in bladder carcinoma cells, in which serum-independent growth of the cells requires the activation of EGFR and Src, which leads to the phosphorylation of Met on Y1003." (PMID 23702846, 2013). "In this study, we examined the mRNA and protein expression of LRIG1 and EGFR in bladder cancers and normal bladder." (PMID 24314030, 2013). "The expression of LRIG1 was decreased, while the expression of EGFR was increased in the majority of bladder cancer, and the ratio of EGFR/LRIG1 was increased in tumors versus normal tissue." (PMID 24314030, 2013). "Epidermal growth factor receptor(EGFR) is a transmembrane protein tyrosine kinase and over-expressed or activated in a variety of malignant lesions, including bladder cancer." (PMID 24314030, 2013). "Owing to the important role of the EGFR activation in bladder cancer growth and progression, therefore, it is a potential target for molecular therapy for invasive bladder cancer." (PMID 24314030, 2013). "In these cell lines, DIM-C significantly sensitized bladder cancer cell lines that were resistant to EGFR inhibition in a schedule-specific manner." (PMID 23409107, 2013). "In a future study, the correlation between apigenin and EGFR expression levels in bladder cancer needs to be examined." (PMID 23724790, 2013).
bladder cancer (continued). "As we build our model around the comparison between EGFR over-expression and FGFR3 activating mutation in bladder cancer, our first simulations were dedicated to the assessment of the model behaviour in these circumstances." (PMID 24250280, 2013). "In order to detect the relationship between LRIG1 and EGFR on bladder cancer cells, we examined the expression level of EGFR on T24 and 5637 cells after transfection of LRIG1 cDNA." (PMID 24314030, 2013). "And we found that EGFR expression is critical for the effect of LRIG1 on bladder cancer cells in vitro." (PMID 24314030, 2013). "In this study, we observed that LRIG1 expression appeared significantly downregulated, but EGFR markly elevated in the majority of bladder cancer compared to human normal bladder tissue." (PMID 24314030, 2013). "Recently, leucine-rich repeats and immunoglobulin-like domains 1 (LRIG1), a negative regulator of EGFR, was discovered is a novel agent for suppressing bladder cancer." (PMID 24314030, 2013). "In order to examine the mRNA expression of LRIG1 and EGFR in bladder cancer, 45 tumor RNA samples and corresponding 5 normal tissues RNA samples were analyzed by quantitative real-time RT-PCR." (PMID 24314030, 2013). "GRB2 is known to be a key molecule in intracellular signal transduction through the EGF receptor (EGFR), and can be overexpressed in tumors of breast and bladder cancers." (PMID 23922722, 2013). "Lipid rafts in vascular smooth muscle cells and bladder carcinoma cells have also been reported to work as a scaffold for Src-EGFR signaling." (PMID 23702846, 2013). "Altogether, these analyses provided novel insights into the mechanisms differentiating the response of urinary bladder cancer cells to EGFR versus FGFR3 stimuli." (PMID 24250280, 2013). "In contrast, the relationship between the AR and EGFR pathways in bladder cancer remains poorly understood." (PMID 22922989, 2012). "Nonetheless, EGFR overexpression is moderately predictive of progression and mortality in patients with bladder cancer." (PMID 22991510, 2012). "Taken together with our previous findings, crosstalk between EGFR and AR pathways can play an important role in the progression of bladder cancer." (PMID 22922989, 2012). "Experimental evidence in bladder cancer has also suggested that the EGFR pathway plays a critical role in cell proliferation, apoptosis, differentiation, migration and angiogenesis." (PMID 22922989, 2012). "The finding supports the importance of the urinary EGF and urothelial EGFR interaction in the pathogenesis of human bladder cancer." (PMID 22991510, 2012). "In contrast, several coexpression patterns were independent prognostic indicators of bladder cancer death, namely, EGFR-ErbB2, ErbB2-ErbB3, and high EGFR or ErbB2 plus low ErbB3 or ErbB4." (PMID 22991510, 2012). "We have recently shown that AR signals increase EGFR and ERBB2 expression and activity, suggesting androgen-mediated bladder cancer progression via the regulation of the EGFR/ERBB2 pathways." (PMID 22922989, 2012). "In bladder cancer, EGFR/ERBB2 is frequently overexpressed, which correlates with higher tumor grade/stage and poorer prognosis." (PMID 22922989, 2012). "Despite the reported over-expression of EGFR in bladder cancer, leading to uncontrolled cell proliferation, increased angiogenesis and reduced apoptosis, to our knowledge, this is the first report regarding the expression of EGF in urinary bladder cancer." (PMID 21483670, 2011). "In bladder cancer, the over-expression of EGFR has been widely reported and several studies have shown EGFR positivity to be associated with high tumor stage, tumor progression, and poor clinical outcome." (PMID 21483670, 2011). "Preclinical studies in bladder cancer cell lines confirm that EGFR inhibitors can inhibit the growth of urothelial cancer cells in vitro." (PMID 21483670, 2011).
bladder cancer (continued). "Sensitivity to the EGFR inhibitor, cetuximab, has been shown to require intact E-cadherin expression and silencing of E-cadherin by RNA interference was reported to reduce responsiveness to EGFR inhibition in previously sensitive bladder cancer cell lines." (PMID 21049033, 2010). "Currently, EGFR targeted treatment is being investigated for bladder cancer in several clinical trials (CALBG-90102, NCT00088946, NCT00380029)." (PMID 21072204, 2010). "Epidermal growth factor receptor (EGFR) is one such molecular marker that has been widely reported in bladder carcinoma." (PMID 19878607, 2009). "The detection of hEGR1 mRNA in varying quantities in all tumour samples used in this study and the significant correlation between hEGR1 and EGFR are an indication of its importance in bladder cancer." (PMID 17311025, 2007). "The effect of EGF and gefitinib on two EGFR-positive human bladder cancer cell lines has been investigated using array-based gene expression profiling." (PMID 17311025, 2007). "Recently, it has been noted that EGFR signalling promotes progression of T24 bladder carcinoma cells via STAT3 upregulation of transcription, including that of matrix metaloproteinases." (PMID 16804520, 2006). "The epidermal growth factor receptor (EGFR) is expressed in a wide variety of epithelial tumours including carcinoma of the bladder." (PMID 15611794, 2005). "Genistein and tyrphostin (an EGFR inhibitor) were both found to preferentially inhibit the motility and growth of bladder carcinoma cell lines that overexpressed EGFR." (PMID 15611796, 2005). "On the other hand, in 11 of 20 (55.0%) patients whose tumours had increased EGFR and/or c-erbB-2 expression, secondary urinary bladder cancers recurred after surgery (P < 0.05)." (PMID 7819052, 1995). "Notably, the prognosis most related to Hub-EGFR.Sig was bladder cancer, which can be divided into two clusters with different responses to immunotherapy based on Hub-EGFR.Sig." (PMID 40574864, 2025). "Protein biomarkers including EDIL-3 (EGF-like repeats and discoidin I-like domains 3) are highly expressed in exosomes derived from high-grade bladder cancer cells and promote tumor migration by activating the EGFR signaling pathway, positioning EDIL-3 as a potential therapeutic target." (PMID 41459253, 2025). "EGFR was phosphorylated in bladder cancer cells by the EC-secreted EGFR ligands and EGFR ligands, including epidermal growth factor (EGF), amphiregulin, epiregulin, betacellulin, tumor necrosis factor-α and epithelial mitogen are upregulated in EC by co-culturing." (PMID 38602556, 2024). "Also, there are more current studies demonstrating EGFR inhibitors in the treatment of bladder cancer in combination treatment with conventional treatments." (PMID 39678505, 2024). "Besides, it was shown that in the cells’ lines of cisplatin-induced bladder cancer, the activity of EGFR (epidermal growth factor receptor) and NF-κB signaling was enhanced, and the expression of ProT was increased." (PMID 39404384, 2024). "In order to confirm the involvement of Fas and EGFR-Ras signaling pathways in the treatment of hyperoside in human bladder cancer cells, Western blotting was performed to detect the expression levels of Fas, EGFR and Ras, which are upstream proteins in the MAPK and Akt signaling pathways." (PMID 38464829, 2024). "Network analysis of the differentially expressed proteins suggested that EGFR-Ras and Fas signaling pathways might play a key role in mediating the effects of hyperoside on bladder cancer cells." (PMID 38464829, 2024). "Interestingly, lower expressions of EGFR, KRT5, and KRT6 are associated with better survival in bladder cancer patients." (PMID 38539513, 2024).
bladder cancer (continued). "The correlative outcomes in this trial will test the hypotheses that apalutamide will decrease EGFR activity and will alter the tumor microenvironment in bladder cancer, including T-cell functional markers." (PMID 38398136, 2024). "Currently available research has reported that LAMC2 and EGFR expressions are positively correlated in bladder cancer, oral (squamous) carcinoma, cholangiocarcionma, as well as in several human cancer cell lines including breast, neoplastic, and ATC cell lines." (PMID 37542131, 2023). "Given the differences in assay platform, time, location, and dosage between the four experiments, it is encouraging to find shared genes that are relevant biologically; EGFR, CDK6, and CDC20 play key functions in cell cycle progression and have been implicated in bladder cancer." (PMID 37415126, 2023). "Similarly, the SE-driven oncogene EGFR contributes to cancer cell migration and invasion, promotes bladder cancer development and progression, and shows prognostic value." (PMID 37501079, 2023). "Overexpression of the EGFR is found in up to 74% of bladder cancer (BCa) tissue." (PMID 37933289, 2023). "We further hypothesized that interruption of this signaling axis with EGFR or NF-κB inhibitors of silencing of ProT or HOTAIR would ameliorate cisplatin-induced bladder cancer cachexia." (PMID 36471329, 2022). "A study indicated that the basal-like bladder cancer subgroup is sensitive to anti-EGFR therapy." (PMID 34991599, 2022). "Additionally, expression of pro-inflammatory cytokines is further elevated in human bladder cancer cells following cisplatin treatment, which can be abrogated by EGFR inhibitors." (PMID 36471329, 2022). "The results of KEGG pathway enrichment analysis showed that the KEGG pathways were mainly involved in signaling pathways regulating stem cell pluripotency, bladder cancer, glycerolipid metabolism, central carbon metabolism in cancer, and resistance to EGFR tyrosine kinase inhibitors." (PMID 35910206, 2022). "Taken together, we conclude that ANXA1 could be considered as an independent prognostic factor, and ANXA1- > EGFR may play critical roles in the tumorigenesis in bladder cancer." (PMID 35784457, 2022). "In summary, we demonstrated that the EGFR inhibitor cetuximab could be an effective targeted therapeutic agent for bladder cancers that require better treatment methodologies." (PMID 36575233, 2022). "Herein, we wondered whether SHCBP1 responds to EGF/EGFR activation through translocation to the nucleus in bladder cancer." (PMID 35013128, 2022). "Interestingly, several of our potential targets are currently in clinical trials for the treatment of bladder cancer including EGFR, HDAC3, FGFR3, ERBB3." (PMID 35035776, 2022). "EGFR activation has also been reported to induce MMP‐9 expression in bladder cancers." (PMID 36448260, 2022). "EGFR plays a crucial role in the METTL1-m7G axis in bladder cancer." (PMID 36468039, 2022). "Therefore, we proposed that cisplatin-induced EGFR activation can upregulate ProT expression via downregulation of miR-1 in bladder cancer cells." (PMID 36471329, 2022). "Furthermore, we identify a novel molecular mechanism involving the EGFR-ProT-NF-κB-HOTAIR signaling axis in bladder cancer cachexia induced by cisplatin chemotherapy." (PMID 36471329, 2022). "Thus, as in bladder cancer, EGFR- and HER2-targeted NIR-PIT would be good target molecules for NIR-PIT in upper tract urothelial cancer." (PMID 35740662, 2022). "Up to seventy-four percent of bladder cancers exhibit EGFR overexpression." (PMID 34206980, 2021). "In addition, the knockdown of XIAP attenuates anchorage-independent cell growth, suggesting that the anchorage-independent growth of bladder cancer can be modulated by the XIAP/miR-200/EGFR/EMT axis (see Section 3.3.2 for EGFR/EMT relationship)." (PMID 33435156, 2021).
bladder cancer (continued). "In patients with bladder carcinoma overexpressing EGFR, treatment with an 213Bi-anti-EGFR-MAb-conjugate resulted in satisfactory therapeutic efficacy, showing that in three of 12 patients no signs of carcinoma in situ were present at 3, 30 and 44 months after treatment." (PMID 33737524, 2021). "In addition, EGFR is an independent predictor of decreased survival and stage progression in bladder cancer." (PMID 34911571, 2021). "Anti-EGFR targeted therapy was extensively studied in advanced urinary bladder cancer." (PMID 34851968, 2021). "We have performed direct investigations of these antitumoral effects through tumor cell migration and cell cycle analysis on two different EGFR overexpressing cell lines, T24 bladder cancer and HeLa cervical cancer cells using miR200c loaded MSN-454-GE11 samples." (PMID 32498278, 2020). "Similarly, EGFR stimulation also leads to signal transduction downstream of the c-Met pathway in bladder carcinoma cells that show moderate levels of EGFR and c-Met expression." (PMID 33195182, 2020). "Similarly, integrin-mediated activation of Src in urinary bladder carcinoma cells leads to a phosphorylation pattern in the kinase domain of EGFR that is different from that induced by the binding of EGF to EGFR." (PMID 32458278, 2020). "In studies of EGFR expression in bladder cancer EGFR overexpression varied strongly between 27 to 74%, which may be due in part to heterogeneous cohorts and different histopathological and molecular subtypes." (PMID 32978523, 2020). "We speculated that the attachment of TiO2-PEG NPs to bladder cancer cells resulted in flocculating of both EGFR and TiO2-PEG NPs." (PMID 31357730, 2019). "Our measurements show, that treatment with 213Bi-anti-EGFR-MAb resulted in a significant decrease of [18F]FDG uptake in EJ28Luc bladder cancer cells, sustaining the hypothesis that alpha radiation results in metabolic alterations." (PMID 31165773, 2019). "Also, bladder cancer cells are sensitive to treatment with drugs that targeting the EGFR pathway, which has been shown to be a therapeutic target in dealing with advanced bladder cancer." (PMID 31871844, 2019). "Blockade of the EGFr pathway may yet be putatively effective in bladder cancer therapy in subgroups of patients with basal muscle-invasive bladder cancer with an activated EGFr signaling pathway." (PMID 29508172, 2018). "Overall, this shows that the EGFR appears to be a feasible target for bladder cancer/NMIBC therapy." (PMID 29701711, 2018). "EGFR expression was confirmed to be elevated in six bladder cancer cell lines." (PMID 29456764, 2018). "Several studies reported over expression of EGFR in bladder cancer." (PMID 29879970, 2018). "NIR-PIT using cetuximab-IR700 conjugate could be applied to other EGFR-expressing cancers in the body such as lung, colon, breast, esophagus, and bladder cancers." (PMID 29721181, 2018). "Nevertheless, there are some cases where the EGFR-targeted radiotherapy could be highly in demand for local administration, for instance, in the case of bladder cancer and brain malignances." (PMID 30510514, 2018). "In large multi-institution retrospective studies, Ki-67, HER-2, EGFR, and N-cadherin were independent prognostic factors for bladder cancer recurrence after RNU and could be used as markers for intravesical therapies and bladder surveillance." (PMID 29135410, 2018). "Overall, given the high amplification rate of EGFR in most bladder cancer cells, EIMPDNEs may provide a selective and improved therapy for NMBIC." (PMID 29701711, 2018). "EGFr may also be involved in the pathogenesis of urinary bladder cancer, i.e., overexpression of EGFr in urinary bladder tumors has been shown to be associated with increased mortality." (PMID 29508172, 2018). "Epidermal growth factor receptor (EGFr)-targeted therapy may be used in subgroups of patients with urinary bladder cancer." (PMID 29508172, 2018).